IDS (iduronate 2-sulfatase)
Diseases named in the same sentence as IDS in open-access papers (continued):
Sharing a sentence is not in itself a finding about the gene and the disease.
Hunter syndrome (continued). "A deficiency of IDS activity results in systemic accumulation of GAGs, leading to a rare metabolic disease, mucopolysaccharidosis type II (MPS II, OMIM 309900), which is also known as Hunter syndrome." (PMID 27695081, 2016). "Mucopolysaccharidosis type II (MPS II) or Hunter syndrome is a lysosomal storage disease caused by a deficiency of the enzyme iduronate-2-sulfatase (IDS)." (PMID 23320174, 2012). "For example, research on delivering a fusion protein consisting of the lysosomal enzyme iduronate 2-sulfatase (IDS) and an anti-human transferrin receptor antibody (JR-141) into the CNS for treating Hunter syndrome has progressed to a phase II clinical trial." (PMID 41012511, 2025). "Pabinafusp alfa consists of human iduronate-2-sulfatase (IDS), the enzyme in which patients with MPS-II are deficient (Hunter syndrome), fused to the C-terminus of the heavy chain of an anti-human transferrin receptor (hTfR) antibody." (PMID 40102994, 2025). "Mucopolysaccharidosis (MPS) type II, or Hunter syndrome, is an X-linked lysosomal storage disorder (LSD) caused by a deficiency of iduronate-2-sulfatase." (PMID 40981299, 2025). "Mucopolysaccharidosis type II (MPS II, Hunter syndrome; # 309900) is an X-linked LSD caused by a deficiency of iduronate 2-sulfatase (I2S, EC 3.1.6.13)." (PMID 39272740, 2024). "Alternatively named as the Hunter's syndrome, MPS type II has an X-linked inheritance and is caused by the defects in the iduronate-2-sulfatase enzyme encoded by IDS gene on chromosome Xq28." (PMID 39044769, 2024). "Hunter syndrome (MPS II), an X-linked recessive lysosomal storage disorder, is a result of deficiency of the iduronate 2-sulfatase enzyme (IDS), leading to cognitive impairment, systemic organ involvement, and increased dental problems." (PMID 38812528, 2024). "Mucopolysaccharidosis type II, also known as Hunter syndrome (OMIM #309900), is a rare X-linked lysosomal storage disorder (LSD) caused by defective iduronate-2-sulfatase (IDS) activity." (PMID 38627369, 2024). "Mucopolysaccharidosis type II [OMIM:309900], also known by the eponym Hunter syndrome, is an XLR LSD resulting from mutations of the gene encoding the enzyme iduronate 2-sulfatase (IDS), located on chromosome Xq28." (PMID 37239976, 2023). "Mucopolysaccharidosis type II (MPS II, OMIM 309900) is an X-linked disorder caused by a deficiency of lysosomal enzyme iduronate-2-sulfatase (IDS)." (PMID 38053930, 2023). "Idursulfase beta, an anti-transferrin receptor antibody fused to iduronate-2-sulfatase based on J-Brain Cargo®, was clinically approved in Japan on 23 March 2021 for the treatment of Hunter syndrome." (PMID 37489365, 2023). "Pabinafusp alfa, which is an anti-mucopolysaccharidosis II drug, consists of iduronate-2-sulfatase (IDS) genetically fused with an anti-transferrin receptor (TfR) antibody." (PMID 40838062, 2023). "JR-141 is an anti-human TfR-human iduronate-2-sulfatase protein conjugate generated to treat the lysosomal storage disease mucopolysaccharidosis II (MPSII)." (PMID 36346674, 2022). "Injection of recombinant iduronate 2-sulfatase (IDS), the enzyme that is mutated in MPSII (Hunter syndrome), into the lumbar CSF resulted in a reduction in CSF GAGs, but had no improvement on cognitive function." (PMID 35745855, 2022). "Mucopolysaccharidosis type II (MPS-II; OMIM Entry #309900), or Hunter syndrome, is a lysosomal storage disease (LSD) resulting from mutations in the iduronate-2-sulfatase gene (IDS, EC 3.1.6.13)." (PMID 35225932, 2022). "Mucopolysaccharidosis type II (MPS II, Hunter syndrome) is a rare, X-linked recessive multisystem lysosomal storage disease due to iduronate-2-sulfatase enzyme deficiency." (PMID 34258227, 2021). "MPS II (Hunter syndrome; OMIM +309900) is an inherited X-linked recessive disease caused by deficient activity of iduronate-2-sulfatase (IDS), which catalyzes a sequential step in the degradation of the GAGs dermatan sulfate and heparan sulfate." (PMID 33622387, 2021).
Hunter syndrome (continued). "Mucopolysaccharidosis type II (MPS II; Hunter syndrome) is an X-linked multisystem disorder characterized by glycosaminoglycan (GAG) accumulation, caused by a deficiency of iduronate-2-sulfatase (I2S)." (PMID 34289859, 2021). "Iduronate 2-sulfatase (IDS), the lysosomal enzyme mutated in Hunter syndrome, was labeled with the [125I]-Bolton-Hunter reagent and the labeled IDS was injected IV in the primate." (PMID 35047884, 2020). "Hunter syndrome, mucopolysaccharidosis type II (MPS II), is an X-linked lysosomal storage disorder characterized by a dysfunctional iduronate-2-sulfatase (IDS) enzyme." (PMID 33124617, 2020). "Hunter syndrome (MPS II) involves iduronate 2-sulfatase (IDS), a key enzyme of the lysosomal dermatan and heparan sulfate degradation pathway." (PMID 32435656, 2020). "Mucopolysaccharidosis type II (MPS II), also known as Hunter syndrome, is a rare X-linked recessive lysosomal storage disease caused by a single gene defect resulting in a deficiency of iduronate-2 sulfatase (IDS) activity." (PMID 32707880, 2020). "The MPS II patients had a clinical diagnosis of Hunter syndrome that was confirmed by biochemical analyses showing a high concentration of urinary GAGs and deficiency in iduronate 2-sulfatase activity in leukocytes." (PMID 32448126, 2020). "Hunter syndrome (MPS II; OMIM 309900) is an X-linked recessive inborn error that causes deficient activity of iduronate 2-sulfatase (IDS, EC3.1.6.13)." (PMID 32448126, 2020). "Clinical trials with TfR antibodies as BBB carriers have been initiated by Roche (to deliver Aβ-antibody for treatment of Alzheimer’s disease) and by JCR Pharma (to deliver iduronate-2-sulfatase enzyme for treatment of Mucopolysaccharidosis II)." (PMID 32698806, 2020). "Mucopolysaccharidosis Type II (MRS II), also known as Hunter syndrome, is a rare X-linked genetic disease caused by mutations in the IDS gene encoding iduronate 2-sulfatase (I2S)." (PMID 31071499, 2019). "Hunter syndrome (mucopolysaccharidosis II; MPS II) is caused by a defect of the iduronate-2-sulfatase (IDS) gene." (PMID 31877959, 2019). "Mucopolysaccharidosis type II (MPS II; Hunter syndrome; OMIM 309900) is a rare, X-linked, life-limiting disease caused by deficient activity of the lysosomal enzyme iduronate-2-sulfatase (I2S; EC 3.1.6.13)." (PMID 29866148, 2018). "Mucopolysaccharidosis I (MPS I; Hurler, Hurler-Scheie, Scheie syndrome) and MPS II (Hunter syndrome) are diseases characterized by deficiencies in the enzymes α-iduronidase (IDUA; EC 3.2.1.76) and iduronate-2-sulfatase (IDS), respectively." (PMID 29801497, 2018). "The ortholog of the human iduronate-2-sulfatase in zebrafish, whose defects are responsible for mucopolysaccharidosis type II (MPS II), has been identified." (PMID 30619849, 2018). "Mucopolysaccharidosis type II (MPS II; Hunter syndrome; OMIM 309900) is a rare X-linked disorder caused by deficient activity of iduronate-2-sulfatase (I2S)." (PMID 28464912, 2017). "Mucopolysaccharidosis type II (MPS II; Hunter syndrome; OMIM 309900) is a rare lysosomal storage disease with progressive multisystem manifestations caused by deficient activity of the enzyme iduronate-2-sulfatase." (PMID 28464912, 2017). "Mucopolysaccharidosis type II (MPS II) is an X-linked recessive, multisystemic lysosomal storage disorder caused by a deficiency of iduronate-2-sulfatase." (PMID 27349225, 2016). "Mucopolysaccharidosis II (MPS II), also called Hunter syndrome, is a rare X-linked recessive lysosomal storage disease caused by iduronate-2-sulfatase enzyme deficiency, leading to accumulation of the glycosaminoglycans, heparan and dermatan sulfate." (PMID 25887606, 2015). "Mucopolysaccharidosis II (MPS II; Hunter syndrome) is an X-linked lysosomal storage disorder (LSD) caused by a deficiency in the enzyme iduronate-2-sulfatase (EC 3.1.6.13), leading to the accumulation of glycosaminoglycans (GAGs) in lysosomes." (PMID 28649553, 2015).
Hunter syndrome (continued). "Mucopolysaccharidosis II (MPS II, Hunter syndrome; OMIM 309900) is a rare, X-linked lysosomal storage disorder caused by a deficiency in the enzyme iduronate-2-sulfatase (I2S), leading to the accumulation of glycosaminoglycans (GAGs) within lysosomes." (PMID 25902842, 2015). "Mucopolysaccharidosis type II (MPS II, Hunter syndrome), is caused by a deficiency of iduronate-2-sulfatase (IDS)." (PMID 26520066, 2015). "Mucopolysaccharidosis type II (MPS II; Hunter syndrome) is an X-linked, recessive, lysosomal storage disorder caused by deficiency of iduronate-2-sulfatase." (PMID 24454794, 2014). "Mucopolysaccharidosis type II (MPS II, Hunter syndrome, OMIM# 309900) is caused by the deficiency of the enzyme iduronate-2-sulfatase (I2S; EC 3.1.6.13) that is responsible for breaking down heparan and dermatan sulfate (HS and DS) within the cells." (PMID 24454794, 2014). "IDS deletions are found in some Hunter syndrome patients, and a more severe Hunter phenotype has been reported in patients with larger deletion regions that include FMR1." (PMID 23634718, 2013). "This deletion resulted in hemizygosity for 113 RefSeq genes including the FMR1 and iduronate 2-sulfatase (IDS) genes which are associated with Fragile X syndrome (FXS) and Hunter syndrome, respectively." (PMID 23634718, 2013). "Mucopolysaccharidosis II (MPS II, Hunter syndrome) is a rare X-linked lysosomal storage disorder caused by the deficiency of iduronate-2-sulfatase (IDS)." (PMID 23497636, 2013). "Hunter syndrome (MPS II; OMIM 309900), is caused by deficiency of the lysosomal enzyme iduronate 2-sulfatase (IDS, EC 3.1.6.13) which functions in the catabolism of two glycosaminoglycans, dermatan sulphate and heparan sulphate." (PMID 21829674, 2011). "Similarly, Hunter syndrome, or Mucopolysaccharidosis type II (MPS II), is an X-linked LSD caused by mutations in the IDS gene, which encodes the enzyme iduronate-2-sulfatase (I2S), essential also for breaking down GAGs." (PMID 41614773, 2025). "Here, we used single-domain antibodies (sdAbs, VHHs) capable of transmigrating the BBB by RMT (referred to as ‘BBB Trojans’), to functionalize CNS delivery of iduronate-2-sulfatase (IDS), an enzyme deficient in patients with mucopolysaccharidosis type II (MPS II; Hunter syndrome)." (PMID 39810248, 2025). "Mucopolysaccharidosis II (MPS II; Hunter syndrome; OMIM 309900) is a rare, progressive, X-linked lysosomal storage disease caused by deficient activity of iduronate-2-sulfatase (I2S), which is responsible for the degradation of the glycosaminoglycans (GAGs) dermatan sulfate and heparan sulfate." (PMID 40598289, 2025). "The first clinically approved therapeutic employing a receptor mediated transcytosis BBB shuttle, pabinafusp alfa, consists of a TfR-binding monoclonal antibody fused to the enzyme iduronate-2-sulfatase, which is defective in mucopolysaccharidosis type II (Hunter syndrome)." (PMID 37620930, 2023). "Indeed, whole IDS gene deletion (with or without the involvement of further neighboring genes) and partial IDS exon deletions have been reported in multiple studies, mainly in patients with a severe Hunter syndrome presentation." (PMID 36009380, 2022). "Mucopolysaccharidosis II (MPS II; also known as Hunter syndrome; OMIM 309900) is a rare, X-linked, life-limiting lysosomal storage disease characterized by a deficiency in the activity of the enzyme iduronate-2-sulfatase (I2S)." (PMID 35620452, 2022). "Mucopolysaccharidosis type II (MPS II; also known as Hunter syndrome) is an X-linked multisystem disorder characterized by glycosaminoglycan (GAG) accumulation, caused by a deficiency of iduronate-2-sulfatase (I2S)." (PMID 34289859, 2021). "Pabinafusp alfa (JR-141), developed by JCR Pharmaceuticals, consists of human iduronate-2-sulfatase (IDS), the enzyme in which patients with MPS-II are deficient (Hunter syndrome), fused to the C-terminus of the heavy chain of an anti-human transferrin receptor (hTfR) antibody." (PMID 34681597, 2021).
Hunter syndrome (continued). "Mutations in the IDS gene lead to a lack of function of the enzyme and are responsible for Mucopolysaccharidosis type II (MPS II, Hunter Syndrome), an X-linked recessive LSD." (PMID 33800050, 2021). "Mucopolysaccharidosis type II (MPS II) is a multi-systemic disorder arising due to pathogenic variants in the gene located on chromosome Xq28 encoding the lysosomal enzyme, iduronate 2-sulfatase (IDS)." (PMID 34258136, 2021). "Mucopolysaccharidosis type II (MPS II) is a lysosomal storage disorder that occurs due to the deficit of the lysosomal enzyme iduronate 2-sulfatase (IDS) that leads to the storage of the glycosaminoglycan heparan- and dermatan-sulfate in all organs and tissues." (PMID 33142967, 2020). "This disease was called Hunter syndrome and is an X-linked genetic disorder characterized by lack of the lysosomal enzyme iduronate-2-sulfatase." (PMID 31152267, 2019). "Recently, the application of this new peptide vector to siRNA and ongoing studies addressing the brain delivery of Iduronate 2-sulfatase (I2S) for the treatment of Hunter Syndrome in knockout mice was discussed at the Brains4Brain society meeting and its results were quite promising." (PMID 28933412, 2016). "Mucopolysaccharidosis type II (MPSII, Hunter Syndrome, MIM: 309900) is caused by mutations in the gene encoding the lysosomal enzyme iduronate 2-sulfatase (IDS), with resulting accumulation of the glycosaminoglycans (GAGs), heparan and dermatan sulfate in the lysosomes." (PMID 27512952, 2016). "Mucopolysaccharidosis type II (MPSII or Hunter syndrome; OMIM +309900) is a rare, X-linked disease characterized by lysosomal accumulation of the glycosaminoglycans (GAGs) heparan and dermatan sulfate due to deficiency of the enzyme iduronate-2-sulfatase." (PMID 27112191, 2016). "Hunter syndrome is a rare (prevalence 1 in 162,000 male live births), X-linked disease caused by a deficiency or absence of the enzyme iduronate-2-sulfatase (I2S), a lysosomal storage enzyme required for the degradation of glycosaminoglycans." (PMID 25836678, 2015). "Intravenous enzyme replacement therapy with iduronate-2-sulfatase is an approved treatment for Hunter syndrome, however, conventional intravenous delivery cannot treat the neurologic manifestations of the disease due to its limited central nervous system penetration." (PMID 25836678, 2015). "Hunter syndrome, mucopolysaccharidosis II (MPS II), is a rare, X-linked, progressive, multi-systemic, lysosomal storage disorder caused by a deficiency of the enzyme iduronate-2-sulfatase with an estimated incidence of 1 per 170,000 male births." (PMID 24806354, 2014). "Hunter syndrome (HS), or Mucopolysaccharidosis type II, is a lysosomal storage disease and a X-linked recessive genetic disorder caused by a mutation in the IDS gene, leading to absence or deficiency of the enzyme iduronate-2-sulfatase (IDS)." (PMID 24083598, 2013). "In couple number 3, the female was a carrier of a deletion of exons 4–7 in the IDS gene, and both members of the couple were also carriers of different mutations in the TYR gene, requiring simultaneous PGD for both Hunter syndrome and oculocutaneus albinism (a recessive disorder)." (PMID 23320174, 2012). "As siblings from the same family may show completely different clinical courses, it is highly likely that in addition to the primary action of IDS gene, other factors modify its effects on the clinical presentation of Hunter syndrome." (PMID 21829674, 2011). "Mucopolysaccharidosis type II (MPS II, OMIM 607014; also known as Hunter syndrome) is a rare X-linked recessive disorder caused by a deficiency of the lysosomal enzyme Iduronate-2-Sulfatase (IDS), leading to the progressive accumulation of Glycosaminoglycans (GAGs) in several organs." (PMID 35882106, 2022).
Hunter syndrome (continued). "Mucopolysaccharidosis type II (MPS II) (Hunter syndrome, OMIM 309900) is an ultra-rare, X-linked multisystem lysosomal storage disease (LSD) due to deficiency of the iduronate-2-sulfatase (I2S) enzyme, caused by spectrum of variants in the IDS gene." (PMID 34258227, 2021). "Mucopolysaccharidosis Type II (MPS II), also known as Hunter syndrome, is a lysosomal storage disorder (LSD) caused by a deficiency of the lysosomal enzyme iduronate-2-sulfatase (IDS)." (PMID 33124617, 2020). "Thus, the girl confirmed comorbidity - Turner syndrome with a partial deletion of the long arm of chromosome X of paternal origin, affecting the Xq28 region (localization of the IDS gene), and Hunter syndrome due to a deletion of the IDS gene inherited from the mother." (PMID 31046699, 2019). "Hunter syndrome was initially considered as a potential diagnosis because the iduronate 2-sulfatase (IDS) gene was located in the deletion region and if it did turn out that Hunter syndrome was the cause of her condition, we could offer our patient therapy through enzyme replacement." (PMID 23634718, 2013). "Mucopolysaccharidosis type II (MPS II, Hunter syndrome, Online Mendelian Inheritance in Man number 309900) is an X-linked, recessive disease that is characterised by deficiency in the activity of the lysosomal enzyme iduronate-2-sulfatase (I2S), owing to a mutation in the I2S gene (IDS)." (PMID 22059643, 2011). "Mucopolysaccharidosis type II (MPS II), also known as Hunter syndrome, is an X-linked recessive lysosomal storage disorder (LSD) caused by deficiency in iduronate-2-sulfatase (IDS) activity, an enzyme responsible for the catabolism of glycosaminoglycans (GAGs)." (PMID 34622797, 2021). "Located next to the IDS gene (90 kb distal), the IDS2 pseudogene, which has a high degree of homology with the IDS gene, makes molecular diagnosis of type II mucopolysaccharidosis difficult." (PMID 31046699, 2019). "However, MPS II (Hunter syndrome) is one of the neuronopathic types of MPS, in which iduronate 2-sulfatase (IDS) function is impaired, resulting in deposition in HS and DS in lysosomes." (PMID 39202222, 2024). "At this moment, Hurler syndrome and Hunter syndrome are considered as candidate diseases, and the aim is to use this IVPRP approach to facilitate the liver to produce in patients therapeutic quantities of the normal enzymes, α-L-iduronidase and iduronate-2-sulfatase, respectively." (PMID 26578156, 2016).